VCAM1 (vascular cell adhesion molecule 1)
Diseases named in the same sentence as VCAM1 in open-access papers (continued):
Sharing a sentence is not in itself a finding about the gene and the disease.
Hyperglycemia (continued). "In summary, STZ-induced hyperglycemia triggers an inflammatory response in the retina of normolipidemic mice and concomitant up-regulation of VCAM-1 in retinal vessels." (PMID 20856927, 2010). "In addition, various factors such as age, sex, metabolic syndrome, hyperglycemia, migraines, and tobacco smoking have been found to affect levels of VCAM-1 and E-selectin." (PMID 39859506, 2025). "The observed increase in VCAM-1 might be attributed to persistent hyperglycemia, leading to the formation of advanced glycation end products (AGEs), or, potentially, be due to insulin resistance." (PMID 39727989, 2024). "Furthermore, ELA administration attenuated adhesive molecules ICAM-1 and VCAM-1 expression under hyperglycemia." (PMID 37540330, 2023). "Additionally, hyperglycemia-induced upregulation of retinal VCAM-1 was significantly greater in retinas of APN-KO mice than in WT mice." (PMID 35264685, 2022). "In addition, APN deficiency resulted in severe vascular permeability under relatively short-term hyperglycemia, together with a significant increase in vascular cellular adhesion molecule-1 (VCAM-1) and a reduction in claudin-5 in the retinal endothelium." (PMID 35264685, 2022). "Hyperglycemia elevates the levels of endothelial adhesion molecules, such as vascular cell adhesion molecule-1 (VCAM-1), via activation of the nuclear factor kappa B (NF-κB) pathway, thus augmenting the interaction between monocyte and endothelium and leading to endothelial inflammation." (PMID 35607953, 2022). "Meanwhile, VCAM-1 was increased as an inflammatory factor by ROS and hyperglycemia in DM group." (PMID 36088760, 2022). "Interestingly, in the T2D patients under treatment (but still with hyperglycemia) we observed increased levels of ICAM-1, VCAM-1 and IL-8 in PBMCs associated to ROCK activation whereas their circulating of both IL-6 and IL-8 were similar to controls." (PMID 32375786, 2020). "Further, PFT‐α and miR‐34a‐I reduced the hyperglycaemia‐induced aortic VCAM‐1 and 4‐HNE levels." (PMID 30793480, 2019). "In addition, GLP-1 is reported to inhibit overexpression of hyperglycemia-induced vascular cell adhesion molecule-1 in vascular endothelial cells." (PMID 25849903, 2015). "Also, hyperglycemia leads to increased production of AGEs which stimulates vascular inflammation and VCAM-1 expression." (PMID 23964833, 2013). "In fact, hyperglycemia-induced monocyte adhesion to cultured aortic ECs in vitro by NF-κB activation increased the expression of pro-inflammatory genes and endothelial adhesion molecules, in particular vascular cell adhesion molecule 1 (VCAM-1) and monocyte chemoattractant protein-1 (MCP-1)." (PMID 26473856, 2015). "In addition to these findings on atherosclerotic plaque formation, GLP-1R agonists prevented the increase in plasminogen activator inhibitor type-1 (PAI-1) and vascular cell adhesion molecule-1 (VCAM-1) gene expression in response to TNF-α or hyperglycemia in HUVEC through PKA pathway." (PMID 25338737, 2014). "Similarly, the PKCβ inhibitor LY379196 prevents hyperglycemia-induced NF-κB activation, VCAM-1 expression, and apoptosis, suggesting PKCβ may be an attractive target to limit diabetes-associated endothelial activation in vivo." (PMID 22489274, 2012). "In vitro studies have demonstrated the dapagliflozin-mediated attenuation of TNF-α- and hyperglycemia-induced increases in ICAM-1, VCAM-1, PAI-1 and nuclear factor-kappa B (NFκB) expression." (PMID 37367894, 2023). "TNF-α and hyperglycemia have been reported to elevate plasminogen activator inhibitor-1 (PAI-1) and ICAM-1 and VCAM-1 expression in endothelial cells." (PMID 37367894, 2023). "Our present study showed that hyperglycemia induced by STZ increased the expression of inflammatory molecules, such as ICAM-1 and VCAM-1, in the aorta, which was suppressed by ipragliflozin treatment." (PMID 27833913, 2016).
Hyperglycemia (continued). "We investigated if citrate treatment of endothelial cells during conditions of hyperglycaemia affects ICAM-1 and VCAM-1." (PMID 22045866, 2012). "Intermittent hyperglycaemia increases oxidative stress‐related cell apoptosis in vascular endothelial cells through PKC‐dependent activation of NAD(P)H oxidase and the expression of several adhesion molecules, such as ICAM‐1, VCAM‐1, and E‐selectin." (PMID 40049179, 2025). "Hyperglycemia and H2O2 can also increase the expression of VCAM-1." (PMID 36088760, 2022). "Hyperglycemia and ROS production also promote TLR-2 and TLR-4 activation, with release of TNF-α, IL-1β, IL-8, monocyte chemoattractant protein (MCP-1), vascular cell adhesion molecule 1 (VCAM-1), intracellular adhesion molecule 1 (ICAM-1)." (PMID 31835864, 2019). "Hyperglycemia could also increase the expression of ICAM-1, VCAM-1, and MCP-1 release." (PMID 22474415, 2012). "In line with this idea, recent in vitro studies using human endothelial cells, demonstrated that hyperglycemia alone was not sufficient to induce expression of VCAM-1, but it significantly enhanced the induction of endothelial VCAM-1 elicited by IL-1β." (PMID 20856927, 2010).
rheumatoid arthritis (67 papers, 2006 to 2025). A chronic, systemic autoimmune disorder characterized by inflammation in the synovial membranes and articular surfaces. "Evidence suggests that VCAM-1 is associated with multiple disorders such as cardiovascular disease, cancer, rheumatoid arthritis, and asthma." (PMID 35336985, 2022). "Dysregulation of VCAM1 expression is indeed linked to several immunological disorders, such as rheumatoid arthritis and asthma." (PMID 36232890, 2022). "The newest data suggest that VCAM-1 is associated with the progression of numerous immunological disorders, such as rheumatoid arthritis, asthma, transplant rejection and cancer." (PMID 35056403, 2022). "The newest data suggests that VCAM-1 is associated with the progression of numerous immunological disorders, such as rheumatoid arthritis, asthma, transplant rejection and cancer." (PMID 35056403, 2022). "Increasing evidence indicates that VCAM-1 is closely linked to the progression of several immunological disorders including rheumatoid arthritis, transplant rejection, asthma, and cancer." (PMID 35832090, 2022). "In the clinical context, there has been a ventricular level increase of VCAM-1 associated with hemodynamic stress in patients with rheumatoid arthritis or intermittent claudication." (PMID 34790706, 2021). "VCAM-1 is a key cell adhesion molecule involved in inflammation that is closely implicated in various immunological disorders, including rheumatoid arthritis, asthma, transplant rejection, and cancer." (PMID 29614819, 2018). "Recent evidence suggests that VCAM-1 is closely associated with the progression of various immunological disorders, including rheumatoid arthritis, asthma, transplant rejection, and cancer." (PMID 29614819, 2018). "High Stro-1 protein expression levels have been observed in OA synovium cell clusters and the soluble form of VCAM-1 has been implicated in rheumatoid arthritis and OA." (PMID 19500336, 2009). "The potential therapeutic applications of the anti-VCAM-1 antibody have been extensively investigated in various conditions, including rheumatoid arthritis, asthma, transplant rejection, and cancer." (PMID 38542876, 2024). "Therapy with methotrexate (MTX) reduced expression levels of E-selectin and VCAM-1 in synovial tissues of patients with rheumatoid arthritis." (PMID 35463298, 2022). "Vascular cell adhesion molecule 1 (VCAM-1) is a cell adhesion molecule and it plays multiple roles in inflammation, cell differentiation and various immunological disorders, including rheumatoid arthritis, asthma, transplant rejection, and cancer." (PMID 35359450, 2022). "VCAM-1 was upregulated in a model of experimental allergic encephalomyelitis and aortic sections in collagen-induced murine model or rheumatoid arthritis." (PMID 35463298, 2022). "It was found by recent researches that Vcam1 plays very important roles in the progression of various immunological disorders, including rheumatoid arthritis, asthma, transplant rejection, and cancer." (PMID 36369435, 2022). "The levels of circulating VCAM-1 in plasma and synovial fluid both were significantly increased in rheumatoid arthritis patients compared to normal controls." (PMID 31013287, 2019). "VCAM-1 expression is raised in acute respiratory distress syndrome, in breast and non-small cell lung cancer, and in rheumatoid arthritis, where it decreases following treatment with infliximab and methotrexate." (PMID 28646244, 2017). "On human articular chondrocytes, however, VCAM-1 appears to play a role in osteoarthritis and rheumatoid arthritis by extravasation of leukocytes from circulating blood to inflamed tissue." (PMID 25993467, 2015). "Elevated vWF and VCAM-1 concentrations as markers of endothelial activation were found together with higher skin autofluorescence in patients with rheumatoid arthritis." (PMID 23671885, 2013).
rheumatoid arthritis (continued). "Most importantly, the expressions of key proinflammatory genes such as Il6, Vcam1, Ccl7, Mmp3, Mmp13, enhanced in rheumatoid arthritis and osteoarthritis, were reduced." (PMID 24199619, 2013). "In line with this assumption, earlier studies described that the IL-18-induced VCAM-1 protein expression in rheumatoid arthritis synovial fibroblasts and the TNF-α-induced VCAM-1 expression in human cardiac fibroblasts are controlled by the Src/PI3K/Akt signaling pathway." (PMID 39768198, 2024). "VCAM-1 relates to the thickness of the carotid intima-media and its plaque in rheumatoid arthritis." (PMID 28646244, 2017). "VCAM-1 might contribute to adhesion of T-lymphocytes to chondrocytes, and thus participate in host defense mechanisms during inflammatory joint conditions such as rheumatoid arthritis or osteoarthritis and/or after cartilage transplantation." (PMID 23285079, 2012). "Intercellular adhesion molecule-1 (ICAM-1) and vascular cell adhesion molecule-1 (VCAM-1) are markers of inflammatory responses involved in various diseases, including asthma and rheumatoid arthritis." (PMID 37228610, 2023). "The primary VLA-4 ligands are the vascular cell adhesion molecule-1 (VCAM-1) and the fibronectin connecting segment-1 (CS1) region during chronic inflammatory diseases, such as rheumatoid arthritis." (PMID 37492575, 2023). "In addition, GZFL had improving effects on articular symptoms and endothelial dysfunction in rheumatoid arthritis (RA) patients by reducing plasma levels of soluble vascular cell adhesion molecule-1 (sVCAM)-1 and lipid peroxide (LPO)." (PMID 35529925, 2022). "IL-18 enhanced the expression of intercellular adhesion molecule-1 (ICAM-1) in human myelomonocytic cell lines, and ICAM-1 and vascular cell adhesion molecule-1 (VCAM-1) in endothelial cells and rheumatoid arthritis synovial fibroblasts." (PMID 33732720, 2021). "The interaction of α4β1 integrin, a major binding partner of VCAM-1, with Ig-like domain 1 or 4 of VCAM-1 is critical for the progression of rheumatoid arthritis, asthma, transplant rejection, angiogenesis, and metastasis." (PMID 29614819, 2018). "Soluble VCAM-1 levels are elevated in several autoimmune diseases that include SLE and rheumatoid arthritis." (PMID 29325582, 2018). "In pathologies such as rheumatoid arthritis, IL-18 has been shown to promote migration, adhesion and activation of leucocytes through the release of different factors such as SDF1/CXCL12 and VCAM1/ICAM1." (PMID 24778454, 2014). "Several studies in systemic autoimmune and chronic inflammatory diseases, e.g., systemic lupus erythematosus (SLE), rheumatoid arthritis, or chronic lung diseases describe increased sCD62L serum levels, together with other elevated adhesion molecules, such as ICAM-1 and VCAM-1." (PMID 32365632, 2020). "An example of this type of molecule was identified as soluble vascular cell adhesion molecule-1 (soluble VCAM-1), and it was reported to be produced in increased concentration in the blood of patients with chronic inflammatory diseases such as rheumatoid arthritis." (PMID 17010215, 2006). "CXCL12, C3, FN1, COL1A2, ACTB, VCAM1, and MMP2 were identified and finally verified as the hub genes, mainly enriched in pathways like leukocyte transendothelial migration, PI3K-Akt signaling pathway, viral myocarditis, rheumatoid arthritis, and platelet activation." (PMID 36398072, 2022).
asthma (61 papers, 2005 to 2025). "Vascular cell adhesion molecule-1 (VCAM-1) has been implicated in recruiting eosinophils and lymphocytes to pathological sites in asthma as a regulatory receptor." (PMID 23855490, 2013). "Furthermore, the cytokines regulated by NF‐κB, including IL‐1β, IL‐2, ICAM‐1, and VCAM‐1 are associated with obese asthma." (PMID 38286741, 2024). "Overall, our results show that PARP-1 plays little to no role in DC differentiation and function and that the protective effect of PARP-1 inhibition against asthma is associated with a prevention of DC migration to the lung through a reduction in VCAM-1 expression." (PMID 31178661, 2019). "Moreover, in asthmatic children, the extent of endothelial dysfunction, as manifested by excess production of circulating vascular cell adhesion molecule-1 (sVCAM-I), was found to be associated with asthma severity, indicating the critical role of ECs in asthma pathogenesis." (PMID 32300593, 2020). "It is known that VCAM-1 interacts with eosinophils via the CD11b receptor in asthma, which promotes their activation." (PMID 40786589, 2025). "Inflammatory molecules, such as matrix metalloproteinases, COX-2, cPLA2, intracellular adhesion molecule-1 (ICAM-1), and vascular cell adhesion molecule-1 (VCAM-1), are implicated in the pathophysiology of respiratory disorders, including asthma and COPD." (PMID 40136649, 2025). "Traditionally, VCAM-1 is known to induce eosinophil transmigration through activated endothelial cells in asthma via interaction with IL-4, which leads to increased release of granule proteins in inflamed tissues." (PMID 40786589, 2025). "Affinity capture studies indicate interactions between the protein products of RPS13, CCT7, and EPS15 and proteins involved in cell–cell and cell-ECM adhesion molecules relevant for asthma, such as VCAM-1, α4β1 integrin, and fibronectin." (PMID 36835202, 2023). "In VCAM-1, a decreasing trend with the severity of allergic asthma was indicated (median 851.00 mild asthma vs. 765.70 moderate asthma vs. 698.15 severe and severe refractory asthma; p = 0.390)." (PMID 36289876, 2022). "Our result for asthmatic patients did not coincide with that of Hamzaoui and colleagues who reported an elevation in serum-soluble E-selectin and VCAM-1 levels in women with severe asthma." (PMID 36289876, 2022). "Injection of anti-VCAM-1, blocking antibodies also inhibits eosinophil recruitment in asthma models in several species." (PMID 32397227, 2020). "More importantly, 11 mRNAs were overlapped in our sequencing data, MalaCards database and asthma-associated genes, including IL4, IL-10, MMP9, VCAM-1, Il1rl1, Alox5, Il1rn, Ccr3, Cysltr1, Epx, and Ccl24." (PMID 31231429, 2019). "Several reports have suggested the importance of the interactions between VCAM-1 and α4β1 integrin in asthma." (PMID 29614819, 2018). "Several studies have shown that VCAM-1 expression is critical for eosinophil infiltration in asthma." (PMID 29614819, 2018). "Periostin and vascular cell adhesion protein 1 (VCAM-1), molecules that mediate leukocyte infiltration and are associated with inflammatory disorders involving marked eosinophilia (e.g. asthma), were particularly elevated in the peritoneum." (PMID 28584245, 2017). "In this regard, we suggest human anti-VCAM-1 mAb treatment as an additional combination treatment option for severe asthma patients reflective of airway remodelling, despite receiving conventional asthma treatment including steroids (inhaled or systemic)." (PMID 23855490, 2013). "Because the VLA-4/VCAM-1 interaction promotes the specific adhesion of eosinophils and not neutrophils, several small molecule inhibitors of the VLA-4/VCAM-1 interaction are under exploration as asthma therapeutics." (PMID 23378838, 2013). "Previous studies have found higher levels of circulating adhesion molecules in COPD patients and having high levels of ICAM-1 and VCAM-1 was related to higher airway resistance in asthma in one study." (PMID 23924044, 2013).